ALDH2 (aldehyde dehydrogenase 2 family member)
Diseases named in the same sentence as ALDH2 in open-access papers (continued):
Sharing a sentence is not in itself a finding about the gene and the disease.
cancer (continued). "Cancer cells overexpressing ALDH2 were inducted for apoptosis." (PMID 35646120, 2022). "In addition, we observed that ALDH2 was differentially expressed between tumor and normal samples in most cancers in the TCGA database through the pan-cancer analysis." (PMID 36144737, 2022). "The associations between these cancers and joint alcohol‐ALDH2‐rs671 groups were broadly similar in never‐regular smokers and in ever‐regular smokers." (PMID 35048370, 2022). "Recent evidence suggested that the ALDH2 gene may be correlated with many cancer developments, such as pancreatic cancer, breast cancer and lung cancer." (PMID 36499358, 2022). "A previous meta‐analysis of case‐control studies found no clear associations of ALDH2‐rs671 with cancers in the liver (1522 cases, 7 studies), colon‐rectum (2356 cases, 10 studies), stomach (5558 cases, 8 studies) or lung (1105 cases, 2 studies)." (PMID 35048370, 2022). "ALDH2 is associated with proliferation, metastasis, and multidrug resistance (MDR) of cancer cells." (PMID 36090994, 2022). "However, the tumorigenesis through metabolism of SLC family and the anti-angiogenesis of TSR1 confirmed in other cancers showed potential interactions between each of them and ALDH2." (PMID 36144737, 2022). "Furthermore, based on the relationship between ALDH2 expression and impute drug response of each patient, we identified the potential roles of ALDH2 in cancer drug therapy." (PMID 35096916, 2021). "We further revealed the clinical value of ALDH2 in cancers subsequently." (PMID 35096916, 2021). "Conversely, ALDH2 presented extensive copy number variation (CNV) in cancers." (PMID 35096916, 2021). "ALDH2 may represent an attractive target for developing of novel cancer therapeutics combined with PD‐1/PD‐L1 blockades." (PMID 34026438, 2021). "Furthermore, univariate Cox regression revealed ALDH2 was a protective factor of survival (disease-specific survival, overall survival, progression-free interval, and disease-free interval) in most cancers." (PMID 35096916, 2021). "Understanding the abnormal expression and genomic alterations of ALDH2 may help elucidate its role in cancer prognosis and therapy." (PMID 35096916, 2021). "We found that ALDH2 expression in most cancers was declined not only in LUAD but also in UCEC." (PMID 34670872, 2021). "Previous studies revealed that ALDH2 plays the dual functions of promoting and inhibiting cancer." (PMID 34026438, 2021). "This study analyzed the expression of ALDH2 and its family genes in 33 cancers." (PMID 34670872, 2021). "Finally, we found that ALDH2 hypermethylation was an essential mechanism in the downregulation of ALDH2 in human cancers." (PMID 35096916, 2021). "Overall, the downregulation of ALDH2 expression tends to suggest malignant phenotypes, which might enhance the precise diagnosis and timely intervention of cancer patients." (PMID 35096916, 2021). "Therefore, a comprehensive understanding of ALDH2 on the molecular characterization and clinical relevance across human cancers is necessary." (PMID 35096916, 2021). "In addition, we have proven ALDH2 has significant clinical value in both large-scale public datasets and 60 pairs of clinical cancer samples." (PMID 35096916, 2021). "Our findings provide new ideas for further research on the regulation of ALDH2 on cancer." (PMID 34670872, 2021). "The aberrant expression of ALDH2 is dramatically correlated with the activity of cancer pathways." (PMID 35096916, 2021). "We also propose that the ratio of XRCC1 and ALDH2 levels may serve as a useful prognostic tool in these cancer types." (PMID 30088263, 2018). "Altogether, this could mean that the BER pathway may be involved in the repair of aldehyde-related DPCs and this, in turn, could explain why low ALDH2 expressing cancer cells have increased BER levels." (PMID 30088263, 2018).
cancer (continued). "Finally, the 30 pairwise head and neck squamous cell carcinomas (HNSCs) from Taiwanese patients were used to compare the ALDH2 genotype with the DEs and cancer prognosis." (PMID 29426835, 2018). "To understand further the relevance of the interplay between XRCC1 and ALDH2 expression in cancer, we investigated whether the profile we observed in most cancers (i.e., low ALDH2 and high XRCC1 mRNA levels) affects patient prognosis." (PMID 30088263, 2018). "We found that the XRCC1 mRNA/ALDH2 mRNA ratio is significantly better at predicting the 5-year overall survival rate for both lung (compare to 3C) and liver (compare to 4C) cancers than ALDH2 levels alone." (PMID 30088263, 2018). "Deficiency in the ALDH2 gene (ALDH2*2 allele) is associated with an increased risk of cancers of the digestive tract, both in alcohol-dependent and non-alcohol-dependent drinkers." (PMID 29342885, 2018). "A point mutation in the ALDH2 gene provides a unique human cancer model for local ACH exposure, the kind of which is not available for any other of the group 1 human carcinogens." (PMID 29303995, 2018). "In addition, we found that Mithramycin A, a XRCC1 expression inhibitor, efficiently kills cancer cells expressing low levels of ALDH2." (PMID 30088263, 2018). "Accordingly, outdated cancer risk assessments of ACH based on experimental animals need to be revised using uniform results obtained from genetic, epidemiologic, and biochemical studies on ALDH2-deficient alcohol consumers compared with ALDH2-active consumers." (PMID 29303995, 2018). "In addition, they reported that heavy drinkers with ALDH2*1/*2 genotype have a 20% cumulative risk of developing UADT cancer by the age of 80 years, while other individuals have < 5% risk of developing UADT cancer by the age of 80 years." (PMID 28253921, 2017). "In addition to these, other cancer stemness associated genes including EPCAM (1.6 folds), ALDH2 (1.3 folds), ALDH1A3 (0.9 folds) and HIF1A (0.7 folds) are all found up-regulated though to less extent." (PMID 28698547, 2017). "Since a high percentage of the East Asian population carries a dominant‐negative allele of the aldehyde‐catalyzing enzyme ALDH2, studies investigating cancer risk associated with BRCA1 and BRCA2 mutations in this population will be important." (PMID 28835508, 2017). "Though study in cancers suggested that hypomethylation of ALDH2 belongs to part of a global DNA methylation change, our study indicated there was just nonsignificant increase in global DNA methylation of myocardial cells after MI, while upstream sequence of ALDH2 core promoter was hypermethylated." (PMID 25629048, 2015). "Hence, ALDH2 is considered to play an important role in cancer treatment." (PMID 35411309, 2022). "Furthermore, ALDH2 is widely used as a marker of cancer stem cells (CSCs)." (PMID 35477569, 2022). "Therefore, ALDH2 inactivation induced by 4-HNE may play an essential role in the progression of some cancer species." (PMID 35517510, 2022). "The multiple roles of ALDH2 in cancers might give rise to diverse reflections on cancer treatments." (PMID 35096916, 2021). "Collectively, ALDH2 might play multiple functional roles in distinct cancers." (PMID 35096916, 2021). "According to the analysis of large-scale public data and 60 pairs of clinical cancer samples, we found the downregulation of ALDH2 expression tends to suggest the malignant phenotypes and adverse prognosis, which might enhance the precise diagnosis and timely intervention of cancer patients." (PMID 35096916, 2021). "Because we did not have information about the presence of the ALDH2 genotype, we could not confirm those results, but the effect of drinking on cancer mortality might differ by genotype." (PMID 33633295, 2021). "Accumulating evidences indicate that dysfunction of ALDH2 may contribute to human cancer." (PMID 33201835, 2020). "Thereby activating ALDH2 might be a potential strategy for the treatment of human cancers." (PMID 33201835, 2020).
cancer (continued). "The link between ALDH2-deficient subjects and an increased risk of UADT cancers is observed in drinkers, possibly due to the increased exposure to acetaldehyde, but not among ALDH2 deficient non- or rare drinkers independently from their smoking habits or diet." (PMID 29342885, 2018). "Altogether, these analyses suggest that the increase in DPCs in cancer cells might be caused by a lack of ALDH2 expression." (PMID 30088263, 2018). "These guidelines do not consider the influence of ALDH2 polymorphism on the association between alcohol drinking and cancer and the amount of alcohol that is considered low risk may not be suitable for individuals with ALDH2 deficiency." (PMID 28253921, 2017). "Dysfunction of ALDH2 in individuals carrying ALDH2 Glu504Lys SNP leads to increased accumulation of toxic aldehydes that may result in higher risk of a variety of human diseases including CVD, cancer, and AD." (PMID 26491656, 2015). "For this, we explored the microbiomes of HFD-fed Aldh2−/−Sptbn1+/− mice, which we refer to as obese TGF-β-driven mouse model of cancer (OTM)." (PMID 40311681, 2025). "The isoforms aldehyde dehydrogenase 1 family member A2 (ALDH1A2), 2 family member (ALDH2), ALDH3A2, and 9 family member A1 (ALDH9A1) were downregulated in all cancers studied." (PMID 40923024, 2025). "The siRNA oligos for GLUL, ALDH2, BLVRA or FBP1 were introduced into cancer tissue derived CA-13 cells." (PMID 38580938, 2024). "Next, we upregulated β-Catenin in ALDH2-overexpressing HCC cells to examine its effect on colony formation and cancer proliferation." (PMID 38725845, 2024). "Recently, isoform‐specific inhibitors are under investigation in cancer research, and some inhibitors can target ALDH1A1, ALDH2, and ALDH3A1." (PMID 36694633, 2023). "We confirmed this experimental observation using ALDH2 inhibitor disulfiram and RAD51 inhibitor B02 in cancer cell lines HCT116 and MCF7." (PMID 36345163, 2023). "The Cancer Cell Line Encyclopedia (CCLE) and the Genomics of Drug Sensitivity in Cancer (GDSC) provide the ALDH2 mRNA levels in 13 HNSC cell lines and the IC50 values for systemic agents (chemotherapy and molecular-targeted treatment)." (PMID 37476181, 2023). "The increased risks among ALDH2‐rs671 AG drinkers, who have markedly elevated acetaldehyde levels after consuming alcohol, but not among never drinkers suggest that acetaldehyde may be the underlying mechanism through which alcohol consumption increases UADT cancer risk." (PMID 35048370, 2022). "The influence of ALDH2 genotype and aldehyde toxicity in the development, progression, and prognosis of UADT cancer in FA patients." (PMID 35330099, 2022). "Furthermore, the effect of ALDH2 polymorphisms on cancer progression is not insignificant." (PMID 36144737, 2022). "Thus, ALDH2 dysregulation may play a role in cancer carcinogenesis and progression." (PMID 36144737, 2022). "Using a combination of biochemical and bioinformatic approach, it was shown that ALDH2 expression was negatively correlated with the level of DNA base excision repair protein, XRCC1, across several cancer types." (PMID 35330099, 2022). "except this, we preliminarily discussed how the changes in ALDH2 are involved in the regulation of cancer and preliminarily verified that miR-301a-5p targets the 3′UTR of ALDH2." (PMID 34670872, 2021). "For example, some genes in the module, such as aldehyde dehydrogenase (ALDH2) and acetyl-CoA carboxylase (ACACA), are known oncogenes, promoting cancer stem cell formation and drug resistance." (PMID 34159316, 2021). "Consistent with the results from the cancer cell lines, targeting BRIP1 as well as several other components of the FA pathway, such as FANCD2 and FANCI, significantly impaired the fitness of ALDH2 KO cells as compared to the WT." (PMID 34454516, 2021).
cancer (continued). "To understand how ALDH2 and BRIP1 levels are regulated in human tumors, we looked at cancer gene expression data obtained from the TCGA and compared them to those found in the normal tissue controls derived from the Genotype-Tissue Expression (GTEx) database." (PMID 34454516, 2021). "According to the classification of normal tissues and tumor tissues, it was found that the expression of ALDH3B1, ALDH18A1, etc., increased in a variety of cancers, but ALDH9A1 and ALDH2 showed the opposite trend in UCEC." (PMID 34670872, 2021). "It has been reported that variants of the ALDH2 gene are correlated with an increased susceptibility to numerous cancers, particularly of the upper digestive organs, such as esophageal or gastric cancer; however, for other cancer types, the results were generally nonsignificant or inconsistent." (PMID 32300124, 2020). "As further proof, our data on downregulation of stemness-related markers, ALDH2 and SOX2, provides additional support for the activity of SNG against cancer stem-like cells." (PMID 32182833, 2020). "Screening the top 200 genes with monotonic expression against the Cancer Gene Census yielded a completely different set of six genes: HSP90AB1, ALDH2, ESR1, PPP2R1A, HIST1H4I, SEPT5." (PMID 31277598, 2019). "It is noteworthy that some isoforms, such as ALDH2, ALDH3A2, ALDH3B1, and ALDH5A1, are expressed at similar levels across cancer types." (PMID 30220009, 2019). "For example, ALDH1A2, ALDH2, ALDH3A2 and ALDH9A1 were downregulated in all tumors among the 5 cancer types, whereas ALDH1B1, ALDH1L2 and ALDH18A1 were most upregulated in tumor parts." (PMID 29426835, 2018). "Globally at the median value, we found that ALDH2 is downregulated by more than two-fold and XRCC1 is upregulated by more than two-fold across all cancer types." (PMID 30088263, 2018). "However, once such role of ALDH2*2 has been proven, the follow-up schedule and methods for alcohol-related cancer patients may be tailored according to their ALDH2 genotypes to increase survival and improve early detection of cancer recurrence or second primary cancer." (PMID 28253921, 2017). "Aldehyde dehydrogenase (ALDH1B1, ALDH2, ALDH3B1, ALDH3B2, ALDH7A1 and ALDH9A1) were involved in the resistance against cyclophosphamide/carboplatin in cancer chemotherapy." (PMID 28225065, 2017). "All these SNP studies have emphasized the important roles of ALDH2 and SOD2 in alcohol drinking and smoking-induced cancer development." (PMID 28841898, 2017). "To examine the prognostic roles of ALDH2, CCNE1 and SMAD3, we tested their protein expressions in FFPE samples of cancer and adjacent normal tissues from 103 patients with UTUC using IHC assay." (PMID 25408144, 2014). "We then dichotomized the 103 patients based on the protein expressions of ALDH2, CCNE1 and SMAD3 in cancer tissues." (PMID 25408144, 2014). "It is worth noting that is famous for its cancer suppression characteristics of ALDH2 in LUAD and GC often lack of expression." (PMID 39328412, 2024). "However, the role of specific ALDH isoforms, such as ALDH1A1, ALDH1A3, ALDH2, and ALDH3A1, as CSC markers has shifted attention towards developing targeted inhibitors to prevent cancer progression." (PMID 38612911, 2024). "Interestingly, disulfiram, a well-known treatment for alcohol abuse, has recently been suggested as a repurposed anti-cancer drug due to its inhibition of ALDH isoforms such as ALDH1A1, ALDH1A3, and ALDH2." (PMID 38612911, 2024). "ALDH2 expression was low in tumor tissues compared to that in normal tissues for most cancers, including lung adenocarcinoma (LUAD) and lung squamous cell carcinoma (LUSC)." (PMID 38292172, 2024). "First, our data did not support the view that ALDH2 should be considered as a cancer therapeutic or prevention target in HBOC." (PMID 36345163, 2023). "In this scenario, cells in ALDH2 defective individuals may have destabilized BRCA2 proteins, forming the basis for haploinsufficiency and accelerated cancer development." (PMID 36345163, 2023).
cancer (continued). "Interestingly, AVPI1, FKBP8, and ALDH2, which were most negatively correlated with NUP205 in LGG, were all reported to be tumor suppressor genes in cancer." (PMID 37284202, 2023). "ALDH2 is a key enzyme that protects the heart from oxidative stress by consuming 4-HNE, and the metabolism of ROS and 4-HNE is thought to be deeply involved in cancer cell death." (PMID 35411309, 2022). "Our studies showed that rucaparib could interact with other biomolecules or cancer-related proteins present in different organelles, which compose a catalytic domain with a NAD+ binding site, such as ALDH2." (PMID 35614267, 2022). "There were no clear differences in cancer risks between ALDH2‐rs671 AG and GG genotypes at the overall level, however, the associations appeared to differ by drinking status." (PMID 35048370, 2022). "This demonstrated the limitations of applying ALDH2‐rs671 directly in MR studies of alcohol and cancer without careful consideration of possible gene‐alcohol interactions." (PMID 35048370, 2022). "Based on this review, the expression level of ALDH2 did not always correlate with the progression in different cancer types." (PMID 35330099, 2022). "Regardless of the cancer types, genes such as ITGA5, SERPINE1, EIF4EBP1 are majorly associated with bad outcomes; while genes such as ALDH2, DBP, FRAT1, PDCD4 are associated with good outcomes." (PMID 35197510, 2022). "Collectively, we have demonstrated ALDH2 is prevalent downregulation in most cancers, which is mainly driven by DNA hypermethylation rather than mutation or CNV." (PMID 35096916, 2021). "The expression of ALDH2 was significantly downregulated across all cancers relative to their corresponding adjacent nontumor tissues (T-test: all P < 0.05)." (PMID 35096916, 2021). "Several of these isoforms have been reported by other groups to be involved in ALDEFLUOR assay, namely ALDH1A1, ALDH1A2, ALDH1A3, and ALDH2, while the other five ones have seldom been described and their role in cancer have not yet been explored in detail." (PMID 30220009, 2019). "We hypothesized that the anticancer effect of bi-TPB-PPB antibodies will become more pronounced when cancer cells are sensitized, for example, by treatment with disulfiram (DSF), a known ALDH2 inhibitor and promising adjuvant for anticancer therapy." (PMID 31700025, 2019). "Apart from research in ALDH1 (ALDH1A1) in cancer stem cells, in fact, research interests in ALDH have been greatly increased recently, especially, ALDH2, because ALDH2 is the most efficient enzyme for the metabolism of ethanol-derived acetaldehyde with the lowest Km." (PMID 29552329, 2018). "Furthermore, 72 cases of ccRCC patients with cancer and corresponding adjacent tissues in database GEO were used to verify the relationship among VHL, HNF-4α and ALDH2." (PMID 28643803, 2017). "In vivo, the impaired FA pathway in double-knockout mice (ALDH2-/-, FAND2-/-) may cause potential cancer initiation even without ethanol administration 5, as other DNA repair processes cannot substitute the FA pathway." (PMID 37476181, 2023). "On the contrary to the expectation from these prior studies, we could not prove the significant impact of ALDH2 genotype on cancer development among our cohort of patients." (PMID 36345163, 2023). "This is supported by our findings of increased UADT cancer risks only among ALDH2‐rs671 AG drinkers but not among ALDH2‐rs671 AG never‐regular drinkers, and the greater excess risks in ALDH2‐rs671 AG drinkers than GG drinkers for a given amount of alcohol consumed." (PMID 35048370, 2022). "Furthermore, ALDH2‐rs671 genotype may modify the effects of alcohol consumption on certain cancers, especially UADT cancers." (PMID 35048370, 2022). "In contrast to the ALDH2‐rs671‐alcohol interactions observed, we found no clear interactions between alcohol consumption and ADH1B‐rs1229984, or between the two genetic variants, on cancer risks, which were largely consistent with previous studies." (PMID 35048370, 2022).